ZFHX2-AS1 (ZFHX2 antisense RNA 1)
Synonyms: LncZFHX2
Gene: Long non-coding RNA gene on chromosome 14 (23,511,760 to 23,560,778, forward strand). Ensembl gene ENSG00000157306.
Diseases named in the same sentence as ZFHX2-AS1 in open-access papers:
ZFHX2-AS1 is named in the same sentence as 1 disease in open-access papers, as found by Europe PMC text mining. Sharing a sentence is not in itself a finding about the gene and the disease.
ZFHX2-AS1 shares sentences with these, for which no sentence is quoted: osteoarthritis (1 paper).